SLC1A2 (solute carrier family 1 member 2)
Description:
Sodium-dependent, high-affinity amino acid transporter that mediates the uptake of L-glutamate and also L-aspartate and D-aspartate. Functions as a symporter that transports one amino acid molecule together with two or three Na(+) ions and one proton, in parallel with the counter-transport of one K(+) ion. Mediates Cl(-) flux that is not coupled to amino acid transport; this avoids the accumulation of negative charges due to aspartate and Na(+) symport. Essential for the rapid removal of released glutamate from the synaptic cleft, and for terminating the postsynaptic action of glutamate (By similarity).
Synonyms: EAAT2; GLT1; GLT-1; HBGT; DEE41; EIEE41
Tractability: Small molecule: a structure with a bound ligand is known; a high-quality ligand is known; it belongs to a druggable protein family. Antibody: UniProt places it where antibodies can reach, with high confidence; its Gene Ontology location is reachable by antibodies, with high confidence; UniProt predicts a signal peptide or a membrane-spanning region. PROTAC: its protein half-life has been measured; a small molecule that binds it is known.
Target class: Transporter; Electrochemical transporter; SLC superfamily of solute carriers; SLC01 family of amino acid transporters
Chemical probes: GT949 (high quality), WAY 213613 (high quality)
Gene: Protein-coding gene on chromosome 11 (35,251,205 to 35,420,063, reverse strand). Ensembl gene ENSG00000110436.
Subcellular location: Cell membrane
Pathways (Reactome):
Neuronal System: Astrocytic Glutamate-Glutamine Uptake And Metabolism; Glutamate Neurotransmitter Release Cycle
Transport of small molecules: SLC-mediated transport of amino acids
Gene Ontology:
Molecular function: glutamate:sodium symporter activity; high-affinity L-glutamate transmembrane transporter activity; L-glutamate transmembrane transporter activity; protein binding; neutral L-amino acid transmembrane transporter activity; cysteine transmembrane transporter activity; monoatomic anion transmembrane transporter activity; symporter activity
Biological process: D-aspartate import across plasma membrane; L-aspartate import across plasma membrane; L-glutamate import across plasma membrane; L-glutamate transmembrane transport; protein homotrimerization; amino acid transport; chemical synaptic transmission; intracellular glutamate homeostasis; L-aspartate transmembrane transport; neurotransmitter transport; transepithelial transport; transport across blood-brain barrier; cellular response to cocaine; cysteine transmembrane transport; glutathione biosynthetic process; import into cell; monoatomic anion transmembrane transport; neurotransmitter reuptake; neutral amino acid transport
Cellular component: cell surface; membrane protein complex; membrane raft; plasma membrane; presynaptic membrane; astrocyte projection; cell body; membrane; axolemma; axon; glutamatergic synapse; neuron projection terminus; synapse; vesicle
Genetic constraint (gnomAD): Loss-of-function variants: 12 observed, 34.17 expected, observed/expected ratio (o/e) 0.35, 90% interval 0.22 to 0.57. The upper end of that interval is the gene's LOEUF score, 0.57, which puts it in group 2 of 6, group 1 being the genes least tolerant of losing a copy. Missense variants: 426 observed, 632.68 expected, observed/expected ratio (o/e) 0.67, 90% interval 0.62 to 0.73. Synonymous variants: 240 observed, 242.82 expected, observed/expected ratio (o/e) 0.99, 90% interval 0.89 to 1.1.
Gene-disease validity (ClinGen):
ClinGen rates the evidence that SLC1A2 causes each of these diseases.
developmental and epileptic encephalopathy, 41 (autosomal dominant): Definitive. Any early infantile epileptic encephalopathy in which the cause of the disease is a mutation in the SLC1A2 gene.
Homologues: Orthologues: chimpanzee SLC1A2 (100% identical), macaque SLC1A2 (99% identical), rabbit SLC1A2 (97% identical), guinea pig SLC1A2 (97% identical), mouse Slc1a2 (95% identical), dog SLC1A2 (93% identical), rat Slc1a2 (91% identical), pig SLC1A2 (86% identical), tropical clawed frog slc1a2 (84% identical), zebrafish slc1a2b (76% identical), zebrafish slc1a2a (75% identical). Paralogues in human: SLC1A1 (46% identical), SLC1A3 (45% identical), SLC1A6 (43% identical), SLC1A7 (41% identical), SLC1A4 (37% identical), SLC1A5 (35% identical).
Diseases named in the same sentence as SLC1A2 in open-access papers:
SLC1A2 is named in the same sentence as 184 diseases in open-access papers, as found by Europe PMC text mining. Sharing a sentence is not in itself a finding about the gene and the disease. The quoted sentences say what the papers report.
epilepsy (71 papers, 2013 to 2025). A brain disorder characterized by episodes of abnormally increased neuronal discharge resulting in transient episodes of sensory or motor neurological dysfunction, or psychic dysfunction. "Recently, the homologous mutation in SLC1A2, predicting P289R EAAT2, was found in patients with early-onset epilepsy and severe developmental delay and was also shown to cause increased activity of EAAT2 anion channels." (PMID 37538371, 2023). "The SOX2-bound genes that are associated with glutamate import and epilepsy were identified as Kcnj10 (Kir4.1), Slc1a2 (GLT-1), and Slc1a3 (GLAST)." (PMID 36543123, 2022). "Previously, three SLC1A2 variants, Gly82Arg, Leu85Pro, and Pro289Arg, were reported to be clinically linked with epilepsy." (PMID 36543780, 2022). "To date, three SLC1A2 variants (Gly82Arg, Leu85Pro, and Pro289Arg) have been reported to be associated with epilepsy; we identified their topological location and the different domains of human EAAT2." (PMID 36543780, 2022). "Previously, three variants (G82R, L85P, and P289R) in SLC1A2 (encoding GLT-1) have been clinically reported to be associated with epilepsy." (PMID 36543780, 2022). "Moreover, impaired function of the glutamate transporter GLT-1 (encoded by Slc1a2) causes excitotoxicity, which is involved in epilepsy pathophysiology." (PMID 41301530, 2025). "Additionally, we established SLC1A2 variant KI mice to provide a basis for the role of GLT-1 in epilepsy." (PMID 36543780, 2022). "Furthermore, we established SLC1A2 variant KI mice to provide a basis for the role of GLT-1 in epilepsy." (PMID 36543780, 2022). "Although SLC1A2 null mice manifest seizures, it is unclear whether locus mutations of SLC1A2 mice lead to epilepsy-associated phenotype." (PMID 36543780, 2022). "Therefore, more clinical studies are needed to validate the efficacy of ceftriaxone in SLC1A2-associated epilepsy." (PMID 36419532, 2022). "SLC1A2 (GLT-1) is a key component of the glutamate/GABA-glutamine cycle, and its mutations can cause impaired glutamate clearance, potentially leading to epilepsy." (PMID 41425581, 2025). "Slc1a2 can genuinely ameliorate epilepsy through the glutamatergic synapse pathway, mitigate neuronal loss, and suppress astrocytosis and inflammatory responses." (PMID 39194497, 2024). "SLC1A2 mutations that predict amino acid exchanges G82R, L85P, or P289R in EAAT2 were reported in three extraordinarily severe cases of epilepsy." (PMID 33587237, 2022). "Among these risk genes, SLC1A2 (which encodes for the excitatory amino acid transporter 2, EAAT2, also called GLT-1) variants, i.e., Gly82Arg, Leu85Pro, and Pro289Arg, are clinically associated with epilepsy." (PMID 36543780, 2022). "Moreover, PTPRM, PPFIA1, SLC1A2, and SGCE were confirmed to be associated with epilepsy, while PTPRD, ASB5, and MCU were involved in neurological disorders." (PMID 29568349, 2018). "However, other top DEGs including CNTNAP4, SLC1A2, and GABRG3 have also been shown to underly irregular firing patterns in the context of epilepsy or autism and could be contributing to the disease mechanism." (PMID 38280846, 2024).
depression (56 papers, 2013 to 2026). "Two different SNPs (rs3812778 and rs3829280) of the SLC1A2 were associated with the level of glutamate within the anterior cingulate in both bipolar and unipolar depression, with minor allele carriers having significantly higher glutamate levels in comparison with common allele homozygotes." (PMID 36233781, 2022). "In the current work, we focus on examining the association of the SLC1A2 rs4354668, SLC6A9 rs2486001, and SLC6A5 rs2000959 polymorphisms with major depressive disorder and its clinical variables in the Polish population." (PMID 36233781, 2022). "Further studies with more SNPs and larger sample size are needed to establish the role of SLC1A2, SLC6A9, and SLC6A polymorphisms in the pathogenesis of depressive disorders." (PMID 36233781, 2022). "Multiple mRNAs regulated by chronic corticosterone exposure in this study are reported to be changed in the same direction in human depression (e.g., downregulation of Gja1, Slc1a2, and Slc1a3)." (PMID 23966905, 2013).
amyotrophic lateral sclerosis (52 papers, 2011 to 2025). Amyotrophic lateral sclerosis (ALS) is a neurodegenerative disease characterized by progressive muscular paralysis reflecting degeneration of motor neurons in the primary motor cortex, corticospinal tracts, brainstem and spinal cord. "The dysfunction of SLC1A2 has been implicated in various neurological disorders, including epilepsy, schizophrenia, and amyotrophic lateral sclerosis (ALS)." (PMID 39100210, 2024). "From this family, SLC1A2 (GLT1) is involved in the pathogenesis of amyotrophic lateral sclerosis (ALS) as well as Alzheimer disease (AD)." (PMID 23506860, 2013). "The relevance of this EAAT2-derived signaling mechanism was demonstrated in vivo, in a mutant SOD1 mouse model of amyotrophic lateral sclerosis (ALS), where knock-in of a modified Slc1a2 isoform with a defective caspase-3 cleavage site prolonged the life span of mice afflicted by the disease." (PMID 35173582, 2021). "In the neurological disorder amyotrophic lateral sclerosis (ALS), increased RNA editing within an intron of the solute carrier family 1 member 2 (SLC1A2) glutamate transporter creates a cryptic PAS resulting in intron retention with termination of transcription transcripts." (PMID 32560344, 2020).
schizophrenia (50 papers, 2004 to 2026). A major psychotic disorder characterized by abnormalities in the perception or expression of reality. "In contrast to bipolar disorder, increased expression of SLC1A2 (along with TGFB2) has been linked to schizophrenia pathogenesis." (PMID 38994948, 2024). "For example, in a Chinese sample, rs12360706 in SLC1A2 was recently found to be associated with schizophrenia, and heterozygotes had a higher proportion of psychosis in their family history." (PMID 36980845, 2023). "Of these, EAAT2 (also known as solute carrier family 1, member 2 encoded by the SLC1A2 gene) has been extensively investigated in schizophrenia pathogenesis." (PMID 36980845, 2023). "Studies showed associations between the SLC1A2 polymorphism and cognitive functions in patients with schizophrenia." (PMID 36980845, 2023). "Previously, a haplotype association between SLC1A2 polymorphisms and schizophrenia in Japanese patients was reported." (PMID 36980845, 2023). "An association of SLC1A2 rs12360706 with schizophrenia was found in the Chinese population, and heterozygotes had a higher proportion of psychosis in their family history." (PMID 36980845, 2023). "SLC1A2 has been implicated in several neurological and psychiatric conditions, including schizophrenia, autism, and bipolar disorder." (PMID 36980845, 2023). "The majority of studies reported an association of SLC1A2 SNPs with bipolar disorder and schizophrenia." (PMID 36233781, 2022). "Genetic variation in SLC1A2 has been implicated in a range of neurological and neuropsychiatric conditions including schizophrenia (SZ), autism and in core phenotypes of bipolar disorder (BD)." (PMID 25406999, 2015). "In this study, the SLC1A2 gene variant, rs4755404, was associated with SA and schizophrenia and other psychotic disorders." (PMID 21711518, 2011). "We concluded that at least one susceptibility locus for schizophrenia is probably located within or nearby SLC1A2 in the Japanese population." (PMID 15296513, 2004). "In this study, we detected significant associations of one haplotype in the SLC1A2 region with schizophrenia in the Kyushu samples." (PMID 15296513, 2004). "In this study we tested associations of schizophrenia with 11 SNPs distributed in SLC1A2 with an average interval of 15.9 kb." (PMID 15296513, 2004). "For instance, rare genetic variation in SLC1A2, necessary for proper synaptic activation and neurotransmission, has been associated with a wide range of neurological conditions including bipolar disorder, schizophrenia and autism." (PMID 28427329, 2017). "However, there is still a possibility that SLC1A2 is a candidate for schizophrenia susceptibility genes, because linkage studies could only detect genes with the large genotype relative risk." (PMID 15296513, 2004). "We examined the association of 39 single nucleotide polymorphisms in eight genes (GRIN2A, GRIN2B, SLC1A2, SLC1A3, SLC17A7, GRM3, GRM7, and GRM8) involved in the glutamatergic system with the development of clinical heterogeneity of schizophrenia." (PMID 36980845, 2023). "As a result of this analysis, associations of four polymorphisms, GRIN2A rs9788936 (p = 0.001), GRIN2A rs8057394 (p = 0.011), GRIN2B rs7313149 (p = 0.016), and SLC1A2 rs12361171 (p = 0.040) with the intensity of symptoms in schizophrenia were identified." (PMID 36980845, 2023). "Recently, we have reported the positive association of SLC1A2 and SLC1A6, the genes encoding EAAT2 and EAAT4, respectively with schizophrenia, providing support for the potential important roles of EAATs in schizophrenia." (PMID 18638388, 2008). "Since located in a putative glycosylation site, the nonsynonymous SNP is potentially involved in the pathophysiology of schizophrenia through affecting the glycosylation status and the transport activity of SLC1A2." (PMID 15296513, 2004). "In this study we report an association study of the excitatory amino acid transporter 2 gene, SLC1A2 with schizophrenia." (PMID 15296513, 2004).
schizophrenia (continued). "Indeed, the SLC1A2 gene is considered a strong candidate for drug dependence and associated psychosis since its variants are hypothesized to be associated with schizophrenia, and schizophrenia’s symptoms, including paranoid hallucinations and delusions, resemble drug-induced psychosis." (PMID 36836504, 2023). "Since EAAT2 accounts for approximately 90% of glutamate reuptake in the rodent forebrain, we focused on the EAAT2 gene (SLC1A2) in association studies of schizophrenia." (PMID 15296513, 2004). "This phenomenon may be compatible with a previous study that did not indicate an association of SLC1A2 polymorphisms with the onset of schizophrenia, which is similar to METH-induced psychosis." (PMID 36836504, 2023). "This study indicates the likely contribution of the GRIN2A, GRIN2B, GRM8, SLC1A2, and SLC17A7 genes to the development of clinical heterogeneity in schizophrenia." (PMID 36980845, 2023). "In the lactate shuttle, six (55%) of the significantly altered genes (n = 11) were upregulated: GLUL, LDHC, SLC16A3, SLC1A2, SLC1A3, and SLC2A1, which were collectively expressed in schizophrenia groups at a level of 1.5× higher than in control groups (LFC = 0.58)." (PMID 39125835, 2024). "In the present study, we were able to detect the contribution of the GRIN2A, GRIN2B, GRM8, SLC1A2, and SLC17A7 genes of the glutamatergic system to determining the clinical heterogeneity of schizophrenia, which is important for the prognosis and outcome of the disease." (PMID 36980845, 2023).
glioma (45 papers, 2012 to 2026). A benign or malignant brain and spinal cord tumor that arises from glial cells (astrocytes, oligodendrocytes, ependymal cells). "SLC1A2, another major membrane glutamate transporter in the CNS, mediates up to 95% of glutamate uptake in the brain and is frequently silenced in gliomas due to DNA methylation." (PMID 25326682, 2014). "In glioma, the decrease in EAAT2 (also known as solute carrier family 1 member 2 (SLC1A2) or glutamate transporter 1 (GLT-1)) correlates with tumor malignancy, making the potential involvement of EAAT in tumor-associated diseases much more relevant." (PMID 37554158, 2023).
Alzheimer disease (44 papers, 2010 to 2026). A progressive, neurodegenerative disease characterized by loss of function and death of nerve cells in several areas of the brain leading to loss of cognitive function such as memory and language. "They found that the supplementation of short-chain fatty acids can significantly regulate neurotransmitter uptake and upregulate genes involved in astrocyte-neuron metabolic coupling (including Glul, Slc1a2, and Gstm1), thereby improving Alzheimer’s disease symptoms in mice." (PMID 39440247, 2024).
Cognitive impairment (35 papers, 2015 to 2025). Abnormal cognition is characterized by deficits in thinking, reasoning, or remembering. "Additionally, an increase in SLC2A2 has been observed due astrocyte activation in AD, while a reduction in SLC1A2, particularly within the hippocampal and prefrontal cortex regions, has been noted in the advanced stages of AD and during the progression of mild cognitive impairment." (PMID 40867161, 2025).
Anxiety (24 papers, 2015 to 2026). Intense feelings of nervousness, tension, or panic often arise in response to interpersonal stresses. "Examining the mRNA SLC1A2, SLC1A3, GRM5, GRIN2B, GRIN2C, GRIA1, CHRNA7, 5-HT2A, and 5-HT3A offers insight into the neurotransmission systems implicated in NP-related anxiety." (PMID 41515464, 2026).
Parkinson disease (23 papers, 2012 to 2025). A progressive degenerative disorder of the central nervous system characterized by loss of dopamine producing neurons in the substantia nigra and the presence of Lewy bodies in the substantia nigra and locus coeruleus. "In addition, Tan et al22 and Cheng et al23 also found a SLC1A2 variant associated with essential tremor but not Parkinson's disease in a Chinese population." (PMID 31755235, 2020).